ELN (elastin)
Diseases named in the same sentence as ELN in open-access papers (continued):
Sharing a sentence is not in itself a finding about the gene and the disease.
atherosclerosis (continued). "Several studies have shown that ISD serves as a biomarker for elastin degradation in many inflammatory arterial diseases including chronic obstructive pulmonary disease (COPD), atherosclerosis, leukocytoclastic vasculitis and abdominal aortic aneurysm." (PMID 28935902, 2017). "Inhibition of miR-181b protects against atherosclerosis and aortic aneurysm through increasing expression levels of macrophage TIMP-3 and vascular smooth muscle cell elastin." (PMID 27756793, 2017). "Tissue from all subjects appeared normal, i.e. without atherosclerosis, calcified areas, or cellular infiltrations, as revealed by von kossa, hematoxylin-eosin, and elastin staining as previously reported." (PMID 22340758, 2012). "Although elastin deficiencies do not lead directly to atherosclerosis, degradation of elastin may allow lipid infiltration into atherosclerotic plaques, leading to the progression of atherosclerosis." (PMID 35229725, 2022). "Hardening of the arteries in elderly suggests that the amount of collagen increases and the amount of elastin decreases with age and progression of the atherosclerosis, but experimental data do not allow for unambiguous confirmation of such hypothesis." (PMID 29305778, 2018). "Taken together, these findings imply a dual beneficial effect of miR-181b inhibition during atherosclerosis and AAAs, namely increased macrophage TIMP-3 protein expression and heightened VSMC elastin production, which could eventually be exploited therapeutically." (PMID 27756793, 2017). "This may have originated from smooth muscle cell proliferation, deposition of lipid, and accumulation of collagen, elastin, and proteoglycans without compensatory development of scar collagen at the early stage of atherosclerosis." (PMID 25369320, 2014). "With the development of a small molecular weight elastin specific gadolinium based MR contrast agent (ESMA), MRI of remodeling at all stages of atherosclerosis has become feasible and has been recently demonstrated in an apoE−/− mouse model of accelerated atherosclerosis." (PMID 24232739, 2013). "The LDL binding is most extensive in the arterial branch points where the elastin layer is absent, indicating that the absence of an elastin layer contributes to the initial LDL infiltration at these sites and the subsequent development of atherosclerosis." (PMID 36359378, 2022). "However, specific labeled molecular MRI targeting tropoelastin suggested a significant accumulation of tropoelastin in atherosclerosis progression, which failed to transfer to mature elastin fibers and could be nonspecifically catalyzed by elastases, leading to further accumulation of EDPs." (PMID 33993833, 2021).
Hypertension (110 papers, 2010 to 2025). The presence of chronic increased pressure in the systemic arterial system. "Hypertension is also known to be associated with the disruption and eventual loss of elastin fibres within the aortic vessel wall." (PMID 40560060, 2025). "Causative role of RAS and elastin degradation (and its replacement by collagen) in hypertension in FGR cohorts has been recently summarised by us and other investigators." (PMID 40253560, 2025). "Conversely, vascular remodelling, such as in the aorta, is a well-known hallmark of hypertension and is closely linked to the loss of elastin fibre integrity within the aortic vessel wall." (PMID 40560060, 2025). "Aging significantly increases the incidence of hypertension, particularly advanced hypertension, and is closely linked to the degeneration of arterial elastin or EFs/EL." (PMID 40001457, 2025). "Hypertension can cause significant alterations to the collagen and elastin composition within arterial walls, thereby contributing to vascular stiffness and remodeling." (PMID 38037153, 2023). "Concomitant high BP and diabetes have been linked to arterial stiffness that facilitates hypertension through a gradual breakdown and loss of elastin fibers in blood vessels, contributing to the development of chronic kidney disease and stroke." (PMID 37315063, 2023). "Previous findings have shown that renal structural and functional abnormalities due to elastin haploinsufficiency precede the development of hypertension, suggesting that the loss of elastin can cause renal dysfunction, at least in animal models." (PMID 37179824, 2023). "Conversely, excessive ISGylation in USP18C61A mice was associated with enhanced angiotensin II-induced hypertension, vascular fibrosis, inflammation, generation of reactive oxygen species (ROS), elastin breaks, and aortic dilation and rupture." (PMID 37025175, 2023). "Hypertension or increased blood flow also contributes to artery tortuosity associated with elastin degradation and fragmentation, which has been considered the cause of vessel lengthening." (PMID 35197040, 2022). "In summary, using a mouse model of elastin insufficiency-mediated hypertension, here we show that loss of AT2R improves blood pressure in this model." (PMID 34790711, 2021). "This vascular aging phenotype is particularly prominent among Asian patients with hypertension, presumably mediated by a continuous loss of elastin content and deposition of interstitial collagen fibrotic replacement." (PMID 32961874, 2020). "It has been shown that lower levels of glycine are associated with impaired collagen and elastin formation in hypertension, causing a reduced elasticity of the arterial wall." (PMID 33187152, 2020). "Further studies on mouse model have linked haplo-insufficiency including elastin gene to increased vascular stiffness and hypertension." (PMID 27525043, 2016). "Elastin is an extracellular matrix protein responsible for the cardiovascular abnormalities associated with Williams’s syndrome, including hypertension and aortic stenosis." (PMID 26167199, 2014). "This raises the possibility that severe hypertension or cardiovascular disease, as would be predicted by a dual state of elastin insufficiency and ApoE deficiency, can cause predisposition to metabolic dysfunction." (PMID 26167199, 2014). "A hallmark feature of Williams-Beuren Syndrome (WBS) is a generalized arteriopathy due to elastin deficiency, presenting as stenoses of medium and large arteries and leading to hypertension and other cardiovascular complications." (PMID 22319452, 2012). "Arterial hypertension is connected with the loss of elasticity, increasing rigidity of the arterial wall and an abnormal increase in collagen/elastin degradation in obese patients with arterial hypertension." (PMID 21247478, 2011).
Hypertension (continued). "Hemodynamic stress due to hypertension induces mechanical fatigue, accelerating medial wall degeneration and loss of elastin elasticity and aberrant collagen deposition impair the ability of the aorta to withstand pulsatile forces, predisposing it to intimal tears." (PMID 40680508, 2025). "Aortic stiffening, which is closely related to variations in the three-dimensional (3D) anisotropic structures of collagen and elastin fibres within the aortic walls, has been recently recognized as both a cause and consequence of hypertension, especially in middle-aged and older individuals." (PMID 40904990, 2025). "Furthermore, vascular growth arrest, impaired elastin synthesis, and nephron deficiency contribute to sustained elevations in blood pressure, establishing an early substrate for hypertension and cardiovascular remodeling." (PMID 41517506, 2025). "For example, small but consistent narrowing/coarctation defects in the descending aortas from 2mth old male Brn-3b KO mice were similar to abnormalities previously shown in heterozygote Eln+/− mice, where reduced elastin was strongly associated with hypertension." (PMID 38007517, 2023). "Owing to the low synthesis of elastin after birth, impaired elastin synthesis during the fetal period may cause decreased compliance of large arteries and even program the development of hypertension and cardiovascular diseases later in life." (PMID 35295253, 2022). "Since elastin laminae run parallel to collagen fibers in the arterial wall, the fracture of elastin caused stress to be transferred directly to the stiffer collagen leading to vascular stiffening and subsequent hypertension." (PMID 35055468, 2022). "The medical treatment is based upon control of other factors which could disrupt the elastin contractile unit, mainly hypertension and other causes of systemic inflammation." (PMID 33807627, 2021). "Decreased levels of glycine in interstitial fluid and plasma, and proline in interstitial fluid may also be associated with a dysregulation in elastin and collagen synthesis associated with hypertension." (PMID 33187152, 2020). "For example, untreated long-lasting hypertension and aging may cause increase in the amount of collagen and decrease in the amount of elastin fibers in the arterial wall." (PMID 21122147, 2010). "In obese adolescents, the main pathological mechanisms behind endothelial damage are processes such as inflammation, dyslipidemia, insulin resistance, and high blood pressure, which may exert stronger effects on vessels than the age-related loss of collagen and elastin." (PMID 36832311, 2023). "Consequently, polymorphisms of the ELN gene may cause a number of vascular diseases, including hypertension, atherosclerosis, and stenosis." (PMID 31138170, 2019). "The loss of elastin may lead to the stiffening of the arterial wall, resulting in hypertension." (PMID 31700728, 2019). "Additionally, the elastic properties of the arterial wall, and in particular the content of elastin and collagen, may be also affected by various risk factors such as hypertension, diabetes mellitus, obesity, smoking, hypercholesterolemia, and kidney disease." (PMID 25803692, 2015). "However, during aging, hypertension, or atherosclerosis, there is a loss of elastin which provides elasticity to the aorta, markedly reducing aortic compliance with the net effect of increasing pulse pressure and systolic pressure (hypertension) and reducing wave reflection at the carotid arteries." (PMID 23243502, 2012). "Hypertension is a leading risk factor for CVD, and it is associated with structural changes, such as medial thickening and a reduced elastin-to-collagen ratio, resulting in stiffer arteries." (PMID 39781517, 2025). "Cardiovascular compliance is known to change with the vascular elastin-to-collagen ratio, a well-established phenomenon in hypertension." (PMID 41150796, 2025).
Hypertension (continued). "SMC-specific TfR1 deletion attenuated medial thickening and elastin fragmentation in both mouse models of hypertension." (PMID 40490490, 2025). "Mechanistically, collagen remains vulnerable to fibrosis while elastin’s production is limited, as its synthesis largely ceases by adulthood, making it more prone to increased proteolytic degradation under hypertension." (PMID 41295367, 2025). "Myh11R247C/R247C aortas have aberrant smooth muscle contractile unit-elastin connections by transmission electron microscopy, along with increased focal adhesion signaling at baseline, which further increases with hypertension." (PMID 40027514, 2025). "Compared to elastin fibres within the aortic internal surface or intima–media, hypertension-induced variations in the corresponding collagen fibres were relatively minor." (PMID 40904990, 2025). "Reduced expression of NCF1 can limit the impact of ELN haploinsufficiency on hypertension by ameliorating the increase of ROS in the vascular walls through regulation of NOX1 and NOX2 NADPH oxidase complexes." (PMID 41292695, 2025). "Hypertension increases the production of collagen fiber and accelerates the degradation of elastin fiber in the vascular system." (PMID 40283461, 2025). "During hypertension, vascular dysfunction drives ECM remodeling- caused by a shift in collagen and elastin balance, which increases aortic stiffness and cardiovascular risk." (PMID 41295367, 2025). "Using this technique, elastin fibre fragmentation, increased collagen content and tunica media thickening in the aortic walls were observed during hypertension." (PMID 40904990, 2025). "Overall, a total of five texture features were identified to quantify hypertension-induced elastin fibre remodelling in aortic internal surface, and most of them are ‘two-factor-related features’." (PMID 40904990, 2025). "Hypertension can lead to shifts in elastin and collagen fiber content within the aorta wall and smooth muscle cells, which are characteristic of aortic aneurysm cases." (PMID 41214542, 2025). "In an ANGII-induced mouse model of hypertension, inhibiting the polarization of M2 macrophages in the aorta reduced abnormal collagen deposition and alleviated elastin fiber fragmentation, effectively improving aortic vascular remodeling." (PMID 38111889, 2023). "Notable genes include ELN, coding for elastic fibers, in connection with connective tissue abnormalities and cardiovascular disease; and NCF1, in connection with the risk of hypertension." (PMID 37759207, 2023). "On the contrary, mice haploinsufficient for elastin (Eln+/−) live a normal life span despite significant hypertension." (PMID 37408270, 2023). "All these metabolic alterations resulted in endothelial dysfunction, increased MMPs and collagen, calcification, and decreased elastin, followed by the development of hypertension." (PMID 35873099, 2022). "Vascular remodeling in hypertension comprises alterations to smooth muscle cells in the artery wall, as well as endothelial cells, elastin, and collagen levels." (PMID 36164390, 2022). "Altered collagen metabolism, higher MMP expression, reduced amount of elastin or compromised fiber assembly, altered ECM composition, generation of elastin derived peptide etc. causes arterial stiffening and leads to hypertension and other complications." (PMID 35783852, 2022). "Adult elastin knockout mice (Eln+/−) have smaller and thinner arteries, increased vessel stiffness, and hypertension that normalizes when the re-expression of elastin is restored." (PMID 34073948, 2021). "While the process of elastin insufficiency is distinct, with normal aging older adults develop vascular elastic fiber thinning, systolic hypertension with widened pulse pressure and large artery stiffness, all characteristics of elastin insufficient mice." (PMID 34790711, 2021).
Hypertension (continued). "The main pathophysiology of a stiffened vasculature is the disrupting elastin in the artery wall, which was proven to predate the subsequent development of hypertension both in mouse models and patients with elastin haploinsufficiency." (PMID 32328303, 2020). "Increase of arterial stiffness, reduction of arterial compliance, and distensibility marked by fragmentation of elastin are the main consequences of arterial remodeling occurring in hypertension, obesity and aging." (PMID 31731463, 2019). "Vascular remodeling in hypertension is characterized by altered ultrastructure due to reduction in elastin and increase in fibrous tissue." (PMID 31731463, 2019). "Insufficient elastin synthesis leads to vascular complications and arterial hypertension in children with Williams-Beuren syndrome." (PMID 31138170, 2019). "During the reconstruction, new elastin and collagen are resynthesized by VSMC, which in turn causes an exacerbation of hypertension." (PMID 31781384, 2019). "A similar link between decreased fenestra area and increased elastin content has been reported in two separate rat models of hypertension." (PMID 27458385, 2016). "Dysregulation of the balance between collagen and elastin, as a result of stimulation by an inflammatory milieu or hypertension, leads to the overproduction of abnormal collagen and reduced quantities of normal elastin, thus contributing to vascular stiffness." (PMID 24755938, 2014). "Their work indicates that abnormalities in elastin deposition at a very young age limit vessel expansion and possibly contribute to hypertension in later life." (PMID 25251068, 2014). "Herein, however, we found that the relative content of elastin remained nearly the same in all arteries over the 8-weeks of hypertension." (PMID 23162468, 2012). "Patients with ELN deletion and only one functional NCF1 allele have a 4-fold decreased risk of hypertension compared with those with more than one copy of NCF1." (PMID 22319452, 2012). "Elastin protein deficiency, due to deletion of one copy of the ELN gene, is responsible for developmental anomalies in arterial wall remodeling, predisposing WBS patients to high blood pressure and other serious cardiovascular complications." (PMID 22319452, 2012). "Experimental models of hypertension in animals suggest that enhanced mechanical stress induced by acutely raising blood pressure increases the synthesis of elastin and collagen in arteries, and this in turn elevates the synthesis of matrix metalloprotinase-9." (PMID 21247478, 2011). "Surprisingly, the absolute content of elastin was increased by L-NAME-induced hypertension and administration of curcumin and/or piperine lead even to its further increase." (PMID 22005253, 2011). "The long-term risk of hypertension associated with dietary factors is significantly amplified by IUGR-induced structural modifications to the ECM, characterized by persistent alterations in elastin composition and increased arterial stiffness." (PMID 40443735, 2025). "Indeed, animal studies have shown that offspring exposed to MDD in utero exhibit reduced elastin content, increased collagen deposition, and elastin fragmentation in the aorta, resulting in arterial stiffening and hypertension." (PMID 39898976, 2025). "Altogether, these results unveiled microstructure-level details of intima–media elastin fibre reorganization induced by age-related hypertension, supporting the hypothesis that hypertension drives aortic fibre remodelling and accelerates ageing." (PMID 40904990, 2025). "Moreover, glycine plays a role in the formation of elastin, which regulates blood vessel elasticity, and changes in vascular elasticity represent another key mechanism in the development of hypertension." (PMID 40661804, 2025).